UCHL1 (ubiquitin C-terminal hydrolase L1)
Diseases named in the same sentence as UCHL1 in open-access papers (continued):
Sharing a sentence is not in itself a finding about the gene and the disease.
liver fibrosis (3 papers, 2017 to 2024). "In support of this idea, active fibrogenesis in a human pre-clinical model of human liver fibrosis was suppressed by UCHL1 inhibition." (PMID 38808772, 2024). "We next asked if inhibition of UCHL1 effects fibrogenesis in a more physiological model of human liver fibrosis." (PMID 38808772, 2024). "A comprehensive cohort study is warranted to access the suitability of UCHL1 as a plasma biomarker for monitoring the progression of liver fibrosis in patients with an HCV infection." (PMID 28667290, 2017). "The data indicate that the expression of UCHL1 is increased in liver fibrosis sections and the plasma of patients with CHC." (PMID 28667290, 2017). "Importantly, pharmacological inhibition of UCHL1 in mouse models of liver fibrosis improves liver fibrosis." (PMID 33261190, 2020). "Here, we describe a role for UCHL1 in regulating the levels and activity of hypoxia-inducible factor 1 (HIF1), an oxygen-sensitive transcription factor, during HSC activation and liver fibrosis." (PMID 38808772, 2024). "This is the first time that HCV-infected hepatocytes were shown to express and secrete UCHL1, which elicits paracrine stimulation of HSC by activating JNK signaling, providing an emerging point for monitoring liver fibrosis and interventional therapy for patients with CHC." (PMID 28667290, 2017). "UCHL1 expression appears as a common molecular change associated with HCV infection and non-viral induced HSC activation and liver fibrosis." (PMID 28667290, 2017). "This is supported by the observations that UCHL1 was expressed in HCV replicon cells and HCV-infected cells, and in the liver fibrosis tissue section obtained from patients with CHC but not CHB." (PMID 28667290, 2017). "Other authors have shown that the ubiquitin C-terminal hydrolase L1 (UCHL1) deubiquitinase is absent in quiescent HSC, but its expression is increased and positively correlates with HSC transdifferentiation in pre-clinical mouse models and clinical liver fibrosis." (PMID 33261190, 2020).
memory impairment (3 papers, 2017 to 2023). "The Uchl1 overexpression, induced by intracranial injection of Uchl1-expressing virus, decreases the Aβ production and protects AD model mice against memory impairment." (PMID 29441009, 2018).
metastatic disease (3 papers, 2009 to 2024). "Interestingly, it was hypothesized that UCHL1 expression may be actively repressed during the initial stages of tumorigenesis, with its re-expression in later stages potentially serving as a reliable indicator of metastatic disease." (PMID 39199615, 2024). "The sizes of metastatic tumors were not affected by overexpression of UCHL1, although UCHL1 has been reported to inhibit NPC cell growth and induce apoptosis in vitro, indicating a primary role of UCHL1 in suppressing metastasis in vivo." (PMID 32120844, 2020).
migraine (3 papers, 2023 to 2025). "Serum levels of UCHL1 were significantly elevated during acute attacks in migraine patients; also, before treatment, UCHL1 levels were significantly and positively correlated with visual analog scores (VAS)." (PMID 39958329, 2025). "Regardless of why t-Tau protein elevation occurs in migraine patients, the lack of difference in concentrations of other biomarkers of neuroaxonal degeneration such as NfL, GFAP and UCHL1 needs to be emphasized and refutes major neurodegenerative processes in migraine." (PMID 38561692, 2024).
multiple sclerosis (3 papers, 2023 to 2025). A progressive autoimmune disorder affecting the central nervous system resulting in demyelination. "Dobson and colleagues observed low UCHL-1 levels in the CSF of patients with multiple sclerosis, which they explained by the sampling occurring in the early stage of the disease." (PMID 39565457, 2025). "This study investigates the significance of glial fibrillary acidic protein (GFAP) and ubiquitin C-terminal hydrolase L1 (UCHL-1) in cerebrospinal fluid (CSF) of patients with multiple sclerosis (MS) and peripheral neuropathy (PN)." (PMID 39565457, 2025).
neuroendocrine carcinoma (3 papers, 2025 to 2026). A malignant neuroendocrine neoplasm composed of cells containing secretory granules that stain positive for NSE and chromogranin. "Similarly, UCHL1 has increased expression in tissues and plasma from patients with neuroendocrine carcinomas, while tumor-derived C3a expression was elevated in serum samples of patients across multiple cancer types." (PMID 39920655, 2025).
neuronal tumor (3 papers, 2014 to 2017). Neuronal brain tumors are an uncommon group of central nervous system tumors that arise from cells with neuronal differentiation. "Although UCHL1 is strongly expressed in neurons, it is also present at high levels in many non-neuronal tumors, implicating that UCHL1 is an oncogene." (PMID 29126443, 2017).
oral squamous cell carcinoma (3 papers, 2019 to 2023). "However, another study reported that in oral squamous cell carcinoma (OSCC), promoter methylation of UCHL1 was higher in OSCC tumours of smokers compared with non-tumour smokers." (PMID 38016026, 2023).
psoriasis (3 papers, 2018 to 2025). An autoimmune condition characterized by red, well-delineated plaques with silvery scales that are usually on the extensor surfaces and scalp. "Thus, essential question has arisen of whether decreased UCHL1 expression in psoriasis might be linked with impaired function of neuro-immune-cutaneous milieu." (PMID 30148172, 2018). "To determine the UCHL1 methylation state we used publicly available datasets, containing methylation microarray information from psoriasis skin samples." (PMID 34272424, 2021). "Accordingly, we have observed that most of the analyzed CpG sites located on UCHL1 promoter were hypermethylated in psoriasis skin samples with respect to controls." (PMID 34272424, 2021). "Inducible expression of UCHL1 was seen in vitro in primary outgrowing keratinocytes arising from psoriasis patients, while in microdissected skin it was only slightly elevated." (PMID 30148172, 2018). "Thus, GADD45α downregulates immune response and inhibits keratinocyte proliferation by increasing UCHL1 demethylation, thereby controlling the progression of psoriasis." (PMID 40083548, 2025). "Interestingly, decreased UCHL1 expression has been detected in skin lesions with itch of psoriasis patients, while an increased number of DCs expressing UCHL1 has been described in atopic dermatitis patients." (PMID 34272424, 2021). "Among analyses of the differential methylation sites (DMS) between psoriasis skin and controls, we have focused on those significant DMS located in CpG islands of the UCHL1 promoter." (PMID 34272424, 2021). "Expression of UCHL-1 was significantly lower in lesional skin compared to both non-lesional skin of psoriasis patients and skin of controls." (PMID 34272424, 2021). "Using siRNA technique, UCHL1/PGP 9.5-expressing cell lines showed more than 200 downregulated and comparable number of upregulated genes engaged in most cellular processes, also those responsible for molecular background of psoriasis." (PMID 30148172, 2018). "The psoriasis patients without itch in nonlesional (mean: 0.001, SD: ±0.00065) and lesional skin (mean: 0.002, SD: ±0.001) did not demonstrate significant differences of UCHL1 expression compared with control group (mean: 0.008, SD: ±0.007)." (PMID 30148172, 2018).
Spastic paraplegia (3 papers, 2021 to 2024). Complete loss of the ability to move the lower limbs accompanied by spasticity of the lower limbs. "In two independent case–control gene burden analyses performed in German and UK cohorts (the latter within the 100 000 genomes project), loss of function heterozygous variants in UCHL1 were found to be enriched in patients with hereditary ataxia and spastic paraplegia." (PMID 39083076, 2024).
Atrophy (2 papers, 2024 to 2025). Any weakening or degeneration, especially through lack of use. "Apoptosis in PT cells results in tubular atrophy with loss of kidney function, and necroptosis participates in the pathogenesis of DKD via the ubiquitin C-terminal hydrolase L1 (UCHL1)-RIPK1/RIPK3 pathway." (PMID 40722167, 2025).
bladder urothelial carcinoma (2 papers, 2020 to 2026). "Moreover, analysis of the TCGA database showed that UCHL1 mRNA was reduced in several types of cancer, including colon adenocarcinoma, kidney renal clear cell carcinoma, kidney renal papillary cell carcinoma, and bladder urothelial carcinoma." (PMID 32120844, 2020). "Moreover, according to analysis from the TCGA dataset, UCHL1 is downregulated in a wide range of cancer types, including colon adenocarcinoma, kidney renal clear cell carcinoma, kidney renal papillary cell carcinoma, and bladder urothelial carcinoma." (PMID 32120844, 2020).
Brain atrophy (2 papers, 2024 to 2026). Partial or complete wasting (loss) of brain tissue that was once present. "Among these, neurofilament light chain (NfL), ubiquitin C-terminal hydrolase L1, total tau, and glial fibrillary acidic protein (GFAP) were consistently associated with CI and brain atrophy across various TBI severities and stages." (PMID 42196255, 2026).
Burkitt lymphoma (2 papers, 2015 to 2023). A rare form of malignant mature B-cell non-Hodgkin lymphoma. "For example, high expression of UCHL1 was noted in Burkitt’s lymphoma and chronic lymphocytic lymphoma cell lines." (PMID 37815895, 2023).
cardiomyopathy (2 papers, 2020 to 2021). A disease of the heart muscle or myocardium proper. "We assumed that miR-1246 might target UBE2C, TNNT1, TRAIP, and UCHL1 during the regulation of ubiquitin-mediated proteolysis, glycosaminoglycan binding, DNA metabolism, the PI3K–Akt–mTOR signaling pathway, the neurotrophin and cardiomyopathy signaling pathway, and the MAPK signaling pathway." (PMID 33050659, 2020).
cognitive decline (2 papers, 2023 to 2025). "The plasma concentrations of Tau, GFAP, NF-L, and UCHL1 correlated with cognitive decline." (PMID 37686075, 2023).
dementia with Lewy bodies (2 papers, 2020 to 2025). "However, UCHL1 levels in CSF have been conflicting, with results from proteomic profiling studies done by mass spectrometry reporting increased UCHL1 in CSF of Lewy body dementia (LBD) and PD patients compared to healthy controls." (PMID 31932518, 2020).
dilated cardiomyopathy (2 papers, 2014 to 2022). Cardiomyopathy which is characterized by dilation and contractile dysfunction of the left and right ventricles. "Upregulation of myocardial UCHL1 was observed in human dilated cardiomyopathy and multiple animal models of cardiac disorders, but the pathophysiological significance of UCHL1 upregulation in the cardiomyocyte compartment has not been established." (PMID 35463782, 2022). "Myocardial upregulation of UCHL1 was observed in human dilated cardiomyopathy and several animal models of heart disease, but the (patho)physiological significance of UCHL1 in cardiomyocytes remains undefined." (PMID 35463782, 2022).
disc degeneration (2 papers, 2022 to 2025). "We identified four genes (SOX9, FLVCR1, NR5A1 and UCHL1) associated with mitochondrial dysfunction that play an important role in the progress of disc degeneration." (PMID 36267810, 2022).
female infertility (2 papers, 2020 to 2025). Diminished or absent ability of a female to achieve conception. "Additionally, loss of UCHL1 is associated with decreased oocyte quality and follicular development, leading to female infertility." (PMID 41430255, 2025).
fibrosis (2 papers, 2020 to 2024). the formation of excess fibrous connective tissue in an organ or tissue in a reparative or reactive process. "Increased expression of UCHL1 has been linked to neurodegeneration, cancer, and fibrosis-associated diseases." (PMID 38808772, 2024). "This study demonstrates that UCHL1 enhances cardiac fibrosis after MI by interacting with and downregulating GRP78 by ubiquitination." (PMID 32606430, 2020). "To determine if UCHL1 regulates cardiac fibrosis, we measured UCHL1 expression in post-MI hearts." (PMID 32606430, 2020). "To assess whether UCHL1 mediates post-MI cardiac fibrosis in vivo, we used LDN to inhibit UCHL1." (PMID 32606430, 2020).
gallbladder carcinoma (2 papers, 2009 to 2024). "Recent reports have emphasized the importance of promoter methylation in specific genes, including CDH1, CDKN2A-p16, REPRIMO (a tumor suppressor gene family), and UCHL1 (also known as PGP9.5) in the development of gallbladder cancer." (PMID 38786750, 2024). "In addition, the silencing or downregulation of UCHL1 mediated by hypermethylation in esophageal squamous cell, hepatocellular and gallbladder carcinoma was correlated in these diseases with a poor prognosis of patients." (PMID 19857250, 2009).
gastric tumors (2 papers, 2024 to 2025). "In this study, we showed that UCHL1 expression was notably elevated in gastric tumors compared with normal gastric tissues." (PMID 41155583, 2025).
glomerulopathies (2 papers, 2015 to 2023). "Interestingly, it was reported that ubiquitin C-terminal hydrolase L1 (UCHL1) is up regulated in a subset of human glomerulopathies, including primary FSGS." (PMID 26301083, 2015).
head and neck cancer (2 papers, 2019 to 2023). A primary or metastatic malignant neoplasm affecting the head and neck. "Notably, our recent study on TCGA- head and neck cancer also identified the overexpression of TRIM16L and UCHL1 in KEAP1-NRF2-CUL3 axis altered patients." (PMID 31839815, 2019).
hilar cholangiocarcinoma (2 papers, 2015 to 2022). A cholangiocarcinoma that arises from the junction, or adjacent to the junction, of the right and left hepatic ducts. "Expression of UCHL1, SNAT1, and EGR1 proteins was predominantly localized to the cytoplasm and was observed in 55.1% (27/49), 55.1% (27/49), and 44.9% (22/49) of hilar cholangiocarcinoma samples, respectively." (PMID 25971332, 2015).
hyperglycaemia (2 papers, 2021 to 2024). "Furthermore, we have shown that these DN-like defects, to be more precise, DSN-like defects, are independent of hyperglycemia and are rather dependent on the increase of insulin resistance specifically in sensory neurons by using UCHL1 transgenic flies and high-sucrose feeding." (PMID 38212312, 2024).
hypoxic-ischemic encephalopathy (2 papers, 2022 to 2024). "It has been reported that UCHL1 is a useful marker that can be helpful in diagnosing acute brain injury and determining the severity of the damage in infants with hypoxic-ischemic encephalopathy." (PMID 36428450, 2022). "After treatment conduction, serum UCHL1 concentrations of calves with perinatal asphyxia gradually decreased at 24, 48, and 72 h compared to the time of admission." (PMID 36428450, 2022). "A significant increase in UCHL1 concentrations in asphyxiated calves may be an indicator of hypoxic-ischemic damage, and we believe that it can be a useful diagnostic marker in the detection of hypoxic-ischemic encephalopathy due to asphyxia in perinatal calves." (PMID 36428450, 2022). "It has been reported that UCHL1 concentrations are higher in foals with hypoxic-ischemic encephalopathy compared to healthy foals, and it can be used as a diagnostic marker to determine HIE-related brain damage in foals." (PMID 36428450, 2022). "Most important, UCHL1 and S100B concentrations were found to be useful markers for the determination of hypoxic-ischemic encephalopathy in calves with perinatal asphyxia." (PMID 36428450, 2022). "UCHL1 and S100B concentrations were found to be useful markers for the determination of hypoxic-ischemic encephalopathy in calves with perinatal asphyxia." (PMID 36428450, 2022). "In our study, the concomitant elevation of S100B, lactate, and UCHL1 concentrations in calves with perinatal asphyxia supports the development of hypoxic-ischemic encephalopathy." (PMID 36428450, 2022). "UCHL1 and S100B were found to be useful markers of hypoxic-ischemic encephalopathy in calves with perinatal asphyxia." (PMID 36428450, 2022). "On the other hand, it was stated that serum UCHL1 concentration increased significantly in foals with neonatal hypoxic-ischemic encephalopathy compared to healthy foals, and UCHL1 could be an important diagnostic indicator in detecting brain damage." (PMID 36428450, 2022).
Insulin resistance (2 papers, 2022 to 2024). Increased resistance towards insulin, that is, diminished effectiveness of insulin in reducing blood glucose levels. "Further studies are needed to fully understand the role of skeletal muscle UCHL1 in lipid metabolism, particularly whether upregulation of UCHL1 in skeletal muscle is involved in metabolic disorders and insulin resistance." (PMID 35464088, 2022).
liver cancer (2 papers, 2018 to 2024). An epithelial or non-epithelial malignant neoplasm that arises from the liver. "For example, in liver cancer samples, the mRNA expression of UCHL1 was higher than that in normal samples, while its protein expression was lower." (PMID 39034372, 2024).
lupus nephritis (2 papers, 2024). Glomerulonephritis in the context of systemic lupus erythematosus. "For example, UCHL1 involves in lupus nephritis and could be a potential target for lupus nephritis." (PMID 38175721, 2024).
malaria (2 papers, 2023 to 2024). Malaria is a serious and sometimes fatal disease caused by a parasite that commonly infects a certain type of mosquito which feeds on humans. "In severe malarial anaemia, elevated ubiquitin C-terminal hydrolase-L1 was associated with worse attention in children <5 years at malaria episode and cognitive testing [β −0.42 (95% confidence interval −0.76, −0.07), P = 0.02]." (PMID 38075948, 2023).
Myocardial fibrosis (2 papers, 2020 to 2022). "Inhibition of UCHL1 with LDN57444 (LDN) reversed the myocardial fibrosis in post-MI heart and improved cardiac function." (PMID 32606430, 2020).
nasopharyngeal tumors (2 papers, 2012 to 2023). "In primary nasopharyngeal tumours, methylation in the UCHL1 promoter region containing these two CpG sites was much higher than in normal tissues and a similar observation was made in oesophageal squamous cell carcinoma primary tumours." (PMID 38016026, 2023).
neonatal encephalopathy (2 papers, 2022 to 2023). "UCHL1 and GFAP have been found to have neuroprognostic importance in infants with neonatal encephalopathy." (PMID 36428450, 2022).
osteoporosis (2 papers, 2023 to 2024). A condition of reduced bone mass, with decreased cortical thickness and a decrease in the number and size of the trabeculae of cancellous bone (but normal chemical composition), resulting in increased fracture incidence. "This is consistent with the phenotype of osteoporosis in mice after osteoclast-specific knockout of UCHL1." (PMID 37215988, 2023). "Quantitative bone morphological parameter evaluation revealed a severe osteoporosis phenotype in UCHL1 cKO-OVX mice, with low bone volume/tissue volume (BV/TV) and trabecular number (Tb." (PMID 37215988, 2023). "We then constructed LysM-Cre-UCHL1f/f mice and found that osteoclast-specific deletion of UCHL1 resulted in severe osteoporosis under pathological conditions, suggesting that UCHL1 exerted an inhibitory effect on osteoclast hyperactivation." (PMID 37215988, 2023). "Osteoclast-specific UCHL1 conditional knockout mice exhibited a severe osteoporosis phenotype in an ovariectomized model." (PMID 37215988, 2023). "However, UCHL1 knockout mice display a phenotype of progressive paralysis, neurodegeneration, and osteoporosis." (PMID 38727276, 2024).
periodontitis (2 papers, 2023 to 2025). An acute or chronic inflammatory process that affects the tissues that surround and support the teeth. "The presence of UCHL1 in periodontitis may be associated with increased inflammation and tissue destruction." (PMID 36982508, 2023). "UCHL1 has been identified as a potential marker for periodontitis." (PMID 36982508, 2023). "UCHL1 may be a potential target for the treatment of AD and periodontitis." (PMID 36982508, 2023).